PTH (parathyroid hormone)
Diseases named in the same sentence as PTH in open-access papers (continued):
Sharing a sentence is not in itself a finding about the gene and the disease.
secondary hyperparathyroidism (continued). "In secondary hyperparathyroidism, serum PTH levels are higher than those in primary hyperparathyroidism." (PMID 23776526, 2013). "In the cross-over study, we conducted a stratified analysis, according to the target int-PTH levels of 60–180 pg/mL, as recommended by the 2006 guidelines for the management of secondary hyperparathyroidism in chronic dialysis patients by JSDT." (PMID 23327614, 2013). "For CKD patients with evidence of secondary hyperparathyroidism, regular monitoring of serum Ca2+, Pi, PTH and vitamin D is necessary." (PMID 23760058, 2013). "Vitamin D has been shown to help decrease PTH levels in primary and secondary hyperparathyroidism and has been used in the treatment of clinically significant FHH." (PMID 22620673, 2012). "The independent predictors of in-hospital death were male sex, elevated PTH and lower leptin levels in patients with cervical HF, and secondary hyperparathyroidism in subjects with trochanteric HF." (PMID 22333003, 2012). "Markedly high levels of FGF23 in combination with parameters of abnormal mineral metabolism are associated with progressive increases in serum intact parathyroid hormone (PTH), referred to as secondary hyperparathyroidism (sHPT)." (PMID 22639045, 2012). "As low 1,25(OH)2D3 stimulates PTH production and secretion, there is secondary hyperparathyroidism in Dmp1−/− mice and PTH suppression in kl/kl mice." (PMID 22879941, 2012). "Conversely, low dietary calcium intake or calcium malabsorption in CD, leads to higher PTH levels (secondary hyperparathyroidism), higher 1,25(OH)2D levels and a reduced half life of 25(OH)D, as well as bone loss." (PMID 23202962, 2012). "There was only one case of secondary hyperparathyroidism detected in the winter (PTH: 81.0 pg/mL, ionized calcium: 1.28 mM, creatinine: 1.5 mg/dL), which normalized in the sample taken in the summer." (PMID 20546572, 2010). "Calcimimetics such as cinacalcet can help reduce parathyroid hormone levels, and hence calcium and phosphorus, in secondary hyperparathyroidism by increasing the sensitivity of calcium sensing receptors in parathyroid gland." (PMID 19646226, 2009). "Although bone histology remains the best method for differentiating between the forms of renal osteodystrophy, serum levels of parathyroid hormone (PTH) are commonly used for diagnosing secondary hyperparathyroidism and OFC." (PMID 19597681, 2009). "It inhibits PTH release and has been shown to be effective in the treatment of CUA in cases where PTH levels were found to be high (secondary hyperparathyroidism)." (PMID 20062786, 2009). "This control over PTH and Ca2+ levels is partially lost in patients suffering from primary and secondary hyperparathyroidism." (PMID 19305800, 2007). "Similarly, vitamin D analogs can treat mineral imbalances and reduce parathyroid hormone (PTH) (secondary hyperparathyroidism), which directly hinders bone production, to enhance bone quality in those with CKD." (PMID 41508850, 2026). "A common complication of CKD is secondary hyperparathyroidism (SHPT), a condition typically marked by elevated intact parathyroid hormone (iPTH) levels and associated symptoms such as bone pain, skeletal deformities, skin itching, and disturbances in calcium and phosphorus balance." (PMID 40837352, 2025). "While secondary hyperparathyroidism (SHPT) is recognized as a risk factor for UTC development, the precise role of PTH in UTC pathogenesis remains unclear." (PMID 41353129, 2025). "Both studies indicate that CKD itself may alter bone’s responsiveness to PTH, but this effect may be masked by naturally progressing secondary hyperparathyroidism." (PMID 40408439, 2025). "Second, the presence of patients with secondary hyperparathyroidism due to chronic kidney disease may have influenced our data as renal function was slightly but significantly worse in the hyper i-PTH group than that in the normal i-PTH group." (PMID 40747083, 2025).
secondary hyperparathyroidism (continued). "Following a reduction of serum calcium levels by cinacalcet, secondary hyperparathyroidism in our patient became more apparent, as her corrected serum calcium levels dropped below the reference range, with high phosphorus and persistently elevated PTH levels." (PMID 41210046, 2025). "Secondary hyperparathyroidism is a common complication of chronic kidney disease due to decreased renal function, leading to increased serum phosphorus and low serum calcium levels, triggering increased secretion of PTH." (PMID 40244253, 2025). "Normocalcemic primary hyperparathyroidism (NPHPT) is regarded as a new phenotype of the disease, characterized by persistent PTH elevation but with normal blood calcium levels and no identifiable causes of secondary hyperparathyroidism or PTH elevation." (PMID 39582410, 2025). "High circulating parathyroid hormone (PTH) leading to secondary hyperparathyroidism is proposed to be a key driver of the skeletal phenotype of chronic kidney disease-mineral bone disorder (CKD-MBD) leading to high bone turnover and cortical bone deterioration." (PMID 40408439, 2025). "Additionally, serum phosphorus levels were significantly reduced in the niacin group, contributing to a 60% decrease in PTH levels, thus mitigating secondary hyperparathyroidism." (PMID 41140700, 2025). "The thiazide challenge test, for example, has been proposed to differentiate renal calcium leak from autonomous parathyroid function: normalization of PTH after a short course of thiazides supports secondary hyperparathyroidism, whereas persistent elevation suggests NPHPT." (PMID 41210508, 2025). "Furthermore, ferric citrate reduced FGF23 levels and lowered the PTH level, thereby exerting effect on secondary hyperparathyroidism." (PMID 40362897, 2025). "Since burosumab inhibits the inhibitory effect of FGF23 on PTH, burosumab may result in increased PTH secretion and the development of secondary hyperparathyroidism." (PMID 40922882, 2025). "Therefore, Epfn is a potential therapeutic target for control of PTH production in primary and secondary hyperparathyroidism patients with CKD." (PMID 40164571, 2025). "The underlying pathophysiological mechanisms include stimulation of Fibroblast Growth Factor (FGF23) and PTH, suppression of 1α-hydroxylase, and direct cellular effects resulting in secondary hyperparathyroidism, impaired mineralization, enhanced bone resorption, and disturbed skeletal homeostasis." (PMID 41303180, 2025). "Moreover, FGF-23-mediated-reduction 1,25(OH)2D levels lead to secondary hyperparathyroidism, and the rise in PTH further augments renal phosphate excretion." (PMID 40362897, 2025). "PTH levels initially decreased to 256 pg/ml, remained stable for a while, and gradually increased to a high of 1205 pg/ml, indicating the onset of secondary hyperparathyroidism." (PMID 41210046, 2025). "Urinary calcium and phosphate excretion may be used as a surrogate for PTH in determining the presence of secondary hyperparathyroidism." (PMID 40003274, 2025). "This heightened risk is predominantly attributed to secondary hyperparathyroidism (SHPT), a frequent complication in CKD characterized by disruptions in the calcium–phosphorus metabolism and the elevated secretion of parathyroid hormone (PTH)." (PMID 40362848, 2025). "Furthermore, researchers found that in murine models affected by secondary hyperparathyroidism, high PTH levels can downregulate ABCG2 expression in renal and intestinal epithelia, resulting in reduced urate excretion and a significant increase in UA levels." (PMID 40710544, 2025). "We showed previously that reduced CaSR expression and increased GABAB1R (encoded by Gabbr1 gene) expression in the parathyroid glands of patients with primary or secondary hyperparathyroidism augmented heterodimerization of the two receptors and increased tonic PTH secretion." (PMID 40492090, 2025).
secondary hyperparathyroidism (continued). "One study that looked at mouse models of FD with impaired functioning of the medullary thick ascending limb of the nephron, observed that a decrease in plasma calcium induced an increase in PTH, leading to secondary hyperparathyroidism, which resulted in accelerated bone resorption." (PMID 40301993, 2025). "The elevated PTH may also indicate secondary hyperparathyroidism, a condition where PTH is elevated due to the body's efforts to maintain normal Ca levels between reduced serum Ca and Vitamin D levels." (PMID 39553143, 2024). "Elevated levels of PTH in combination with low serum 25-hydroxyvitamin D, even without secondary hyperparathyroidism, have also been associated with both increased bone turnover and mortality." (PMID 39592711, 2024). "Actually, the effect on PTH may also be dependent on the secondary hyperparathyroidism severity, and higher levels of 25(OH)D are required, or the PTH decrease depends on the 1,25(OH)2D correction." (PMID 38397979, 2024). "Elevated PTH in patients with CKD-MBD defines secondary hyperparathyroidism." (PMID 39364464, 2024). "Notably, PTH levels usually decrease, but persistent secondary hyperparathyroidism is described in 10 to 60% of patients 12 months post-KTx with hyperparathyroidism being an independent risk factor for allograft dysfunction in pediatric KTx." (PMID 39384649, 2024). "Considering the progeric and uremic conditions characterizing progressive kidney disease, once the PTH levels have taken off the normal range, there are presumably few physiological mechanisms left in order to attenuate the inevitable development of secondary hyperparathyroidism." (PMID 38785509, 2024). "However, hemodialysis patients with a lower average intact serum PTH display a significantly higher risk of non-fatal cardiovascular events compared to patients with serum PTH values in the range of secondary hyperparathyroidism." (PMID 38785509, 2024). "By contrast, the proportion of patients within the recommended ranges for phosphorus and parathyroid hormone was higher in 2023 (68% and 76%, respectively), denoting the greater expertise of nephrologists in treating bone disease and secondary hyperparathyroidism." (PMID 39115840, 2024). "Additionally, using an AD with 1.25 mmol/L of calcium is known to increase PTH levels and worsen secondary hyperparathyroidism over time." (PMID 39126060, 2024). "However, patients with ARD had, on average, an increased PTH concentration for any plasma 25(OH)D range, suggesting impaired vitamin D metabolism and a higher proportion of secondary hyperparathyroidism." (PMID 36815008, 2023). "A reference value of PTH >47 ng/L was considered secondary hyperparathyroidism." (PMID 38126603, 2023). "Similarly, inhibition of the ERK pathway by FGF23 stimulates the release of PTH in rats with secondary hyperparathyroidism." (PMID 37065733, 2023). "When stratifying patients according to PTH values, patients displaying PTH > 200 pg/mL (and, thus, considered to have secondary hyperparathyroidism) had significantly higher preptin levels compared to patients considered to not have secondary hyperparathyroidism." (PMID 37755271, 2023). "Among the underlying causes, mineral metabolism alterations have been implicated, including derangement of calcium-phosphate homeostasis, which leads to secondary hyperparathyroidism (sHPT) characterized by elevated parathyroid hormone (PTH) levels and parathyroid hyperplasia." (PMID 36678208, 2023). "However, the PTH remains the main biochemical marker used to monitor the progression of patients with secondary hyperparathyroidism." (PMID 38075043, 2023). "Consequently, the level of serum PTH increases (called secondary hyperparathyroidism) to maintain serum calcium through increasing renal tubular calcium reabsorption and bone resorption." (PMID 37481570, 2023). "CKD often results in secondary hyperparathyroidism due to elevated PTH levels." (PMID 38276262, 2023).
secondary hyperparathyroidism (continued). "In addition, for both primary and secondary hyperparathyroidism patients, it was certain that the levels of PTH, calcium and phosphorus after both types of ablation were closer to the normal level compared with those before ablation." (PMID 36892812, 2023). "An intact 1,25(OH)2D3-VDR system is important for both basal and PTH-induced osteoclastogenesis; 1,25(OH)2D3 administration inhibits PTH synthesis and parathyroid cell growth, thus rendering 1,25(OH)2D3 therapy effective in treating the secondary hyperparathyroidism of chronic kidney disease (CKD)." (PMID 36556093, 2022). "Furthermore, an independent relationship exists between obesity and increased parathyroid hormone (PTH), which is exacerbated by the reduction of vitamin D, contributing to the presence of secondary hyperparathyroidism (SHPT) well before BS." (PMID 36382751, 2022). "Reported biochemical features of secondary hyperparathyroidism include elevated parathyroid hormone (PTH), serum calcium (Ca), alkaline phosphatase (ALP) levels and low levels of phosphate (P), Radiographic findings in neonates resemble changes of rickets and/or hyperparathyroidism." (PMID 35268460, 2022). "Some authors speculate that the presence of severe skeletal changes related to secondary hyperparathyroidism indicate that the abnormal elevation of PTH starts in utero." (PMID 35268460, 2022). "Studies observed that a value of 38 ng/mL of vitamin D may be sufficient to avoid an increase in PTH, and vitamin D supplementation with calcidiol improved serum 25(OH)D while significantly lowering PTH levels and reducing secondary hyperparathyroidism." (PMID 36014846, 2022). "In addition, 25(OH)D deficiency can cause secondary hyperparathyroidism (SHPT), and high parathyroid hormone (PTH) levels can inhibit insulin secretion, further aggravating IR." (PMID 34807347, 2022). "VD deficiency may result in inadequate circulating calcidiol levels, which decreases calcitriol synthesis and calcium absorption, leading to an increase of PTH levels, a condition known as secondary hyperparathyroidism." (PMID 35353297, 2022). "At the same time, glucocorticoids cause decreased intestinal calcium absorption and increased calciuria, causing a severe decrease in serum calcium levels and, thus, inducing a strong stimulation of PTH production and leading to the establishment of secondary hyperparathyroidism." (PMID 36714597, 2022). "The patient, male, 49 years old, underwent related examinations due to generalized weakness and pain in both lower extremities a month ago, Parathyroid Hormone (PTH): 3000pg/mL, had a history of chronic renal failure for more than 10 years, and was diagnosed as secondary hyperparathyroidism." (PMID 36401397, 2022). "Several studies showed that 25OHD levels below 20 ng/mL may be correlated with secondary hyperparathyroidism, and that PTH levels reached a plateau for 25OHD levels between 30 and 40 ng/mL." (PMID 35893864, 2022). "Elevated serum PTH levels might be indicative of a secondary hyperparathyroidism-like state, which may contribute to the accelerated bone loss in Dmp1-PPRKO mice." (PMID 34968192, 2021). "Calcimimetics activate the CaSR to reduce PTH secretion and prevent secondary hyperparathyroidism." (PMID 33416083, 2021). "In addition, ferric citrate reduced FGF23 levels by more than half and also lowered the intact PTH (iPTH) level, thereby exerting effect on secondary hyperparathyroidism." (PMID 34069053, 2021). "Targeting CaSR in the parathyroid gland by the FDA-approved drug cinacalcet or other calcimimetics suppresses parathyroid hormone (PTH) secretion, which is commonly used to treat secondary hyperparathyroidism associated with chronic kidney disease or renal failure." (PMID 33400691, 2021).
secondary hyperparathyroidism (continued). "Serum intact PTH, calcium, and phosphate levels were 489 ± 285 pg/mL, 9.6 ± 0.4 mg/dL, and 6.2 ± 1.3 mg/dL, respectively, indicating that all had secondary hyperparathyroidism according to the 2006 Japanese Guidelines for management of secondary hyperparathyroidism in dialysis patients." (PMID 33976330, 2021). "Because secondary hyperparathyroidism (with an intact parathyroid hormone [PTH] level of 1630 pg/mL) resistant to conservative treatment was considered a causative factor, surgical PTX was performed with autotransplantation into the subcutaneous tissue of the non-shunt side forearm." (PMID 34479496, 2021). "However, with the progression of kidney disease, a reduction in the levels of 1,25(OH)2D3 persists in addition to a secondary increase in PTH levels, leading to the development of secondary hyperparathyroidism." (PMID 33869246, 2021). "The Vdr null mice fed a regular diet, which have secondary hyperparathyroidism, may have enlarged lacunae in part be due to enhanced PTH action." (PMID 34043707, 2021). "Secondary hyperparathyroidism is characterized by an increased level of serum parathyroid hormone." (PMID 32569210, 2020). "This may be related to the higher preoperative PTH level than normal due to the secondary hyperparathyroidism effect." (PMID 32555278, 2020). "It is well described that low levels of 25(OH)D may elevate the levels of parathyroid hormone (PTH), causing secondary hyperparathyroidism (SHPT)." (PMID 32375334, 2020). "Only one out of the four patients with secondary hyperparathyroidism had their PTH level normalized by Day 7, which was associated with the normalization of the 25(OH)D3 level (39.4 ng/mL on Day 7 vs. 7.1 ng/mL on Day 0)." (PMID 33352890, 2020). "In our center, we usually perform total parathyroidectomy ± auto-transplantation for the dialysis patients who have persistent secondary hyperparathyroidism (PTH levels > 800 pg/mL) and are accompanied by clearly related signs and symptoms and refractory to medical therapies." (PMID 32183885, 2020). "Since secondary hyperparathyroidism is very frequent in the elderly population and has harmful consequences (especially for bone mass), 25(OH)D concentrations above 30 ng/mL have been recommended for normalization of PTH levels in this population." (PMID 32813765, 2020). "Vitamin D can regulate secretion of some hormones, including parathyroid hormone (PTH), insulin, and fibroblast growth factor 23 (FGF23), and the effects on PTH secretion are facilitated by using vitamin D analogues in the clinical treatment of secondary hyperparathyroidism." (PMID 32316584, 2020). "Therefore, the prevention of secondary hyperparathyroidism or an increase in serum PTH concentration is recommended to ameliorate the bone abnormalities present in patients with ESKD." (PMID 32582730, 2020). "Secondary hyperparathyroidism (SHPT) is a complication of chronic kidney disease (CKD) in patients undergoing hemodialysis, caused by the parathyroid gland overproducing parathyroid hormone (PTH)." (PMID 30159688, 2019). "The absolute lack of insulin secretion leads to PTH hypersecretion, associated with a decrease in serum Ca2+ levels and causes a secondary hyperparathyroidism." (PMID 31933638, 2019). "This elevated PTH level in VDD is called secondary hyper-parathyroidism (SHPT)." (PMID 31491937, 2019). "Secondary hyperparathyroidism (PTH greater than 47.7 pmol/L) was found in 31.8% of the patients." (PMID 31846484, 2019). "In patients with chronic kidney disease (CKD), the loss of the regulatory kidney function triggers a cascade of processes eventually leading to secondary hyperparathyroidism, an abnormality characterized by increased PTH synthesis and secretion, and PTG cell proliferation." (PMID 30927339, 2019).